SNORA74C-1 (small nucleolar RNA, H/ACA box 74C-1)
Gene: Small nucleolar RNA gene on chromosome 10 (45,984,610 to 45,984,810, forward strand). Ensembl gene ENSG00000265733.
Gene Ontology:
Biological process: RNA processing
Cellular component: nucleolus
Homologues: Orthologues: chimpanzee SNORA74 (94% identical), macaque SNORA74 (93% identical), dog SNORA74 (87% identical), pig SNORA74 (83% identical), rabbit SNORA74 (83% identical), mouse Gm23946 (76% identical), guinea pig SNORA74 (74% identical), rat LOC120097670 (70% identical), tropical clawed frog SNORA74 (62% identical), tropical clawed frog SNORA74 (61% identical), tropical clawed frog SNORA74 (60% identical), tropical clawed frog SNORA74 (49% identical). Paralogues in human: SNORA74C-2 (98% identical), SNORA74B (88% identical), SNORA74 (71% identical), SNORA74 (70% identical), SNORA74A (58% identical), SNORA74 (55% identical), SNORA74D (35% identical), SNORA74 (34% identical).